NOX4 (NADPH oxidase 4)
Diseases named in the same sentence as NOX4 in open-access papers (continued):
Sharing a sentence is not in itself a finding about the gene and the disease.
diabetes (continued). "The results of the present study suggest that OMT alleviates diabetes-associated cognitive decline, oxidative stress, and apoptosis via NOX2 and NOX4 inhibition." (PMID 33273999, 2020). "Our previous study demonstrated that endothelial dysfunction following diabetes was due to upregulated expression of NOX4 in the thoracic aorta, which resulted in increased oxidative stress in diabetes." (PMID 33273999, 2020). "Growing evidence suggest that the members of the pro-oxidant Nox family, particularly Nox4 and Nox5 isoforms, are the key contributors of renal ROS generation in diabetes." (PMID 33396868, 2020). "PRR-KO in diabetic mice significantly (P<0.05) reduced the observed diabetes-induced increase of NOX-4 expression by 49%." (PMID 31800607, 2019). "Experimental models have identified a role for Nox1, Nox2, and Nox4 in various cardiovascular pathologies, including hypertension, atherosclerosis, cardiovascular and renal complications of diabetes, and pulmonary hypertension." (PMID 30334629, 2019). "We tested the expression of NOX4, the major NAD(P)H oxidase isoform in cardiomyocytes, which is associated with cardiomyopathy in the diabetes model." (PMID 30710997, 2019). "In conclusion, increased expression of PRR localized in renal mitochondria and diabetic kidney induced mitochondria dysfunction, and enhanced renal apoptosis and fibrosis in diabetes by upregulation of mitochondria NOX4/SOD2/UCP2 signaling pathway." (PMID 31406124, 2019). "To assess the possible effect of HG on ROS-generating enzyme expression, we analysed the expression of NOX4, which is a key enzyme related to diabetes known to increase ROS levels in podocytes under various conditions." (PMID 31488111, 2019). "It has also been demonstrated that in the setting of diabetes, NOX4 deletion results in a dedifferentiation of the SMC and increased proliferation." (PMID 32923955, 2019). "In conclusion, this study shows, for the first time, that PPARβ/δ activation confers vascular protection against oxidative stress in diabetes via direct induction of HO-1 and downregulation of NOX-4 and, to a lesser extent, NOX-2." (PMID 30046379, 2018). "Genetic deletion of Nox4 in ApoE−/− mice increased atherosclerosis after 20 weeks of diabetes mellitus induction, while deletion of Nox1 in the same conditions reduced atherosclerosis." (PMID 29710840, 2018). "The upregulation of Nox4 in the mitochondria was observed in a model of diabetes in rat, mainly in the cortex of kidney cells." (PMID 29710840, 2018). "Summer in both species and diabetes in rats downregulated myocardial Nox4 while reciprocally upregulating Nox2 and Nox5 in guinea‐pigs, and Nox2 in rats." (PMID 29084841, 2017). "In the case of NOX4, diabetes also increased the mRNA levels (p < 0.05), and in the diabetes + exercise group, this increase was even more pronounced, although with substantial variability." (PMID 28698769, 2017). "The literature has reported beneficial roles of Nox4 in experimentally induced diabetes and atherosclerosis 37,38." (PMID 28591344, 2017). "Amongst these, the Nox4 gene, a biomarker of oxidative stress in the diabetic mellitus, has particularly high expression in the kidney." (PMID 27706190, 2016). "Our previous study suggests that upregulation of Nox4 in retinal endothelial cells contributes to retinal vascular leakage in diabetes." (PMID 25866826, 2015). "These include an antisense approach and the use of pharmacological inhibitors, both studies indicating that decreased Nox4 activation confers renal benefits in the setting of experimental diabetes." (PMID 25367693, 2014). "We have shown for the first time the renoprotective effects of global deletion of Nox4 in a model of streptozotocin‐induced diabetes." (PMID 25367693, 2014). "The diabetes‐induced increase in albuminuria in wild‐type diabetic (WT‐D) mice was ameliorated in the Nox4−/− diabetic mice (KO‐D)." (PMID 25367693, 2014).
diabetes (continued). "Global deletion of Nox‐4 in a streptozotocin model of diabetes was able to attenuate a number of important renal functional and structural parameters including albuminuria and extracellular matrix accumulation." (PMID 25367693, 2014). "Deletion of Nox4 appears to be effective in reducing the burden of renal disease in diabetes, as reflected by reduced glomerular injury and thus represents a potentially important therapeutic target for diabetic nephropathy." (PMID 25367693, 2014). "Immunostaining of renal cortex revealed that major isoforms of PKC, PKC‐α and PKC‐β1, were increased with diabetes and normalized by Nox4 deletion." (PMID 25367693, 2014). "The proposed studies will provide ‘proof of concept’ that targeting Nox4 will attenuate, or reverse the development of renal fibrosis in patients with diabetes mellitus." (PMID 23991195, 2013). "Using an STZ diabetes mouse model, we have demonstrated that Nox4 protein and ROS production are increased in the diabetic kidneys and their expression is largely localized to the tubules." (PMID 23991195, 2013). "Diabetic kidneys had increased transcript and membrane-bound protein levels of Nox4, the renal-specific generator of cytosolic reactive oxygen species (ROS) and reduced expression of SOD2, UCP2, GPX3, NQO1, and CAT." (PMID 23149823, 2013). "It is possible that diabetes induced ROS production is reduced by plumbagin and the downstream limitation in tubulointerstitial damage reduces Nox4 tissue expression." (PMID 23991195, 2013). "Recent studies showed that Nox4 localizes in mitochondria and that, in the animal model of diabetes, ischemic stroke and nephrotoxicity drugs, mitochondrial Nox4 expression is increased." (PMID 23349934, 2013). "NOX4 (NADPH oxidase 4) is the major source of ROS in the kidneys during early stages of diabetes, and NOX4-derived ROS mediates renal hypertrophy and increased fibronectin expression." (PMID 19471607, 2008). "Having identified a likely important role for NOX4 in mediating CB-ECFC stimulated pro-angiogenic response in experimental diabetes, we isolated CB-ECFCs from donors with gestational diabetes as a more clinically relevant model of chronic disease to assess NOX4 impact." (PMID 40457435, 2025). "Having highlighted NOX4 signalling as a likely important regulator of angiogenic response in healthy CB-ECFCs exposed to experimental diabetes, we investigated whether migratory and tubulogenic function could be rescued by NOX4OE in this setting." (PMID 40457435, 2025). "Ezetimibe also ameliorated cardiac interstitial fibrosis and coronary arterial thickening, indicating that NOX4 may contribute to cardiovascular complications in diabetes." (PMID 41009041, 2025). "In a rat model of diabetic cardiomyopathy using streptozotocin-induced diabetes, treatment with antisense oligonucleotides targeting NOX4 attenuated NOX activity, NOX4 protein expression and ROS generation in the left ventricle, and improved cardiac systolic dysfunction." (PMID 41009041, 2025). "The aim of this study was to specifically investigate impact of experimental and clinical diabetes on CB-ECFC angiogenic function in relation to NOX4 signalling towards identification of key mediators as candidates for selective targeting to enhance therapeutic efficacy in this setting." (PMID 40457435, 2025). "Altogether, these findings suggest that NOX4 may play a role in the cardiac complications of diabetes, and that targeting its expression could offer therapeutic benefits." (PMID 41009041, 2025). "Taken together, these data indicate a central role for NOX4-dependent downstream signalling in protecting ECFC proliferative capacity in diabetes which may serve to promote heightened cell resilience and survival within hostile tissue environments." (PMID 40457435, 2025). "Furthermore, our recent study shows that endothelial cell (EC)-specific deletion of Nox4 prevents diabetes-induced vascular leakage and acellular capillary formation in the retina." (PMID 38748682, 2024).
diabetes (continued). "Whether NOX4 or other NADPH oxidases cause ferroptosis in pancreatic β-cells, thereby inducing or exacerbating diabetes, requires further investigation." (PMID 38693581, 2024). "Indeed, targeting NOX4 via genetic deletion or pharmacological inhibition afforded renoprotection, as reflected by the attenuation of diabetes-induced enhanced albuminuria, renal inflammation, and fibrosis via a reduction in ROS formation." (PMID 38671844, 2024). "Expanding on previous findings, this study examined the role of endothelial cell-specific NOX5 expression in an STZ-induced insulin-deficient diabetes mouse model in the presence or absence of NOX4 expression." (PMID 38671844, 2024). "Previously, we have shown that Nox4 upregulation in retinal endothelial cells by diabetes leads to increased vascular leakage by an unknown mechanism." (PMID 38748682, 2024). "However, the increased renal expression of NADPH-oxidase-4 (Nox4) was downregulated by EC-NOX5 expression in cases of diabetes." (PMID 38671844, 2024). "Using animal models with excess dietary fat, our present study demonstrated that ASMase is likely a culprit for high glucose, PA and C16-Cer stimulated ROS production by regulation of NADPH oxidases, mainly is NOX4.NOX4 is a major source of cytosolic ROS, which initiate oxidative stress in diabetes." (PMID 36732747, 2023). "Thus, this research aimed to study the effect of diabetes on cardiac NOX4 and SRIT-1 protein levels as antigenic factors." (PMID 36721814, 2023). "In addition, mounting evidence has revealed that NOX4 plays an important role in many diseases by producing ROS, and NOX4 inhibition exerts protective effects in lung, liver and heart disease as well as diabetes." (PMID 35441079, 2022). "NOX4 has also been shown to be atheroprotective in diabetes." (PMID 35617030, 2022). "Podocyte-specific NOX4 knockout also reduces albuminuria, and improves glomerular sclerosis, mesangial expansion, and glomerular basement membrane thickness in streptozotocin-induced diabetes of mice." (PMID 36297636, 2022). "Besides, NOX4 can increase plaque burden with less T‐cell activation and infiltration in a 10‐week model of diabetes, but conversely, in the 20‐week model of diabetes, NOX4 can decrease collagen deposition and proliferation, blocking advanced lesions." (PMID 35386842, 2022). "NOX4 is the most abundantly expressed NOX isoform in the kidneys, and NOX4-derived ROS overproduction in mesangial, endothelial, and tubular cells has been associated with kidney disease related to diabetes and obesity." (PMID 36611880, 2022). "Thus, ROS generated by NADPH oxidase-4 leads to mobilization of TRPC6 in podocytes and NOX4 knockout is protective in STZ-induced diabetes and is associated with markedly reduced Ca2+ influx in podocytes from diabetic Dahl SS rats." (PMID 36421724, 2022). "Interestingly, we found that only 3 genes out of 92 were altered in CECs by HuR deletion and diabetes: HuR, Cx40, and Nox4." (PMID 34747371, 2021). "This review describes the key roles of Nox2 and Nox4, as well as Nox1 and Nox5, in glucose homeostasis, endothelial function and oxidative stress, with a key focus on how they are regulated in health, and dysregulated in type 2 diabetes mellitus." (PMID 34571964, 2021). "According to a previous report, inhibition of PKCβ signaling attenuates diabetes-induced NOX4 expression and oxidative stress, consistent with our results showing that CTRE inhibits MGO-induced PKCβ activation, subsequently inhibiting NOX4 expression in HK-2 cells." (PMID 33859775, 2021). "However, this diabetes-induced elevation in Nox4 expression was markedly reduced with CL treatment, back to control levels." (PMID 33967810, 2021). "Early studies of miR-25 in a rat diabetes model demonstrated miR-25 downregulated Nox4 expression." (PMID 34571964, 2021). "In addition, NOX4 activation, which serves as the predominant source of O2· production, is observed in diabetes-induced vascular dysfunction." (PMID 33273999, 2020).
diabetes (continued). "Indeed, increased expression of renal Nox4 and Nox5 have been demonstrated in the human diabetic kidney, as well as in renal cells, in response to high glucose and diabetes-induced AGE accumulation, angiotensin II and TGF-β." (PMID 33396868, 2020). "To summarize, our study provided evidence that punicalagin can alleviate diabetic nephropathy, and the effect is associated with downregulating the expression of NOX4, inhibiting TXNIP/NLRP3 pathway-mediated pyroptosis, suggesting its therapeutic implications for complications of diabetes." (PMID 32456088, 2020). "Whether other forms including Nox2 and Nox4 are altered as a function of diabetes remain to be explored." (PMID 30720765, 2019). "Thus, the importance of NOX4 and CPT1A as molecular targets for therapies aimed at attenuating inflammasome activation has been implicated in diabetes or metabolic diseases." (PMID 30728885, 2019). "In our experiments using isolated glomerular samples, low- and high-dose ipragliflozin reduced synaptopodin expression and subsequent oxidative stress within glomeruli; however, only high-dose ipragliflozin ameliorated the diabetes-induced up-regulation of Nox4 in glomeruli." (PMID 29507299, 2018). "Conversely, NOX4 decreased following Egr1 knockdown in HK-2 cells and diabetic kidney mice." (PMID 29854821, 2018). "Nox1, but not Nox4, seems to be important in atherosclerosis in diabetes, as we demonstrated in Nox1-deficient mice on the atherosclerosis-prone ApoE−/− background made diabetic with streptozotocin." (PMID 29459239, 2018). "Therefore, the PPARβ/δ-induced suppression of NOX-4 can significantly improve the integrity and prevent injury of the vasculature in diabetes." (PMID 30046379, 2018). "Nox4 was reduced in plaques from patients with cardiovascular events or diabetes." (PMID 28587189, 2017). "In contrast to NOX4 isoform-derived reductive stress, a sustained increase in oxidative stress due to aging and chronic pathological conditions such as diabetes and inflammation may impact on EPC numbers and functions." (PMID 28386230, 2017). "The summer in guinea‐pig and rat heart, and diabetes in rat heart and rat kidney, all consistently resulted in the many‐fold increases in the Nox2 protein expression and simultaneously in the prominent Nox4 protein downregulation." (PMID 29084841, 2017). "Finally, the physiological role of Nox4 is unclear, as it has been reported to have various roles in hypertension, atherosclerosis and diabetes." (PMID 28591344, 2017). "Under certain conditions, such as the release of transforming growth factor-β1, diabetes, and heart failure, Nox4-dependent H2O2 formation may become harmful." (PMID 29135921, 2017). "Importantly, since NOX4 is a direct target of miR-2537, the resultant decreases in miR-25 can lead to enhance NOX4 expression (and related oxidative stress) as seen in diabetes." (PMID 27941951, 2016). "We found that mRNA levels of Nox4 were significantly increased in the glomeruli of the diabetic mice compared to control, but Seven in Absentia Homolog 1 (Siah1) mRNA expression was significantly decreased in diabetes compared to control." (PMID 27941951, 2016). "The GSI, a measure of glomerular damage, was increased with diabetes in the Nox4 WT‐D mice." (PMID 25367693, 2014). "Mean systolic blood pressure was unaffected by induction of diabetes or deletion of Nox4." (PMID 25367693, 2014). "In this study, global deletion of a NADPH‐oxidase isoform, Nox4, was examined in mice with streptozotocin‐induced diabetes (C57Bl6/J) in order to evaluate the effects of Nox4 deletion, not only on renal structure and function but also on the PKC pathway and downstream events." (PMID 25367693, 2014). "This study suggests that deletion of Nox4 may alleviate renal injury via PKC‐dependent mechanisms, further strengthening the view that Nox4 is a suitable target for renoprotection in diabetes." (PMID 25367693, 2014).
diabetes (continued). "Our data provide evidence that Nox4 expression, ROS production, and endothelial inflammation were strongly upregulated in the HG/thrombin-stimulated HAECs, further supporting Nox4-mediated vascular complications in diabetes." (PMID 25298619, 2014). "It has been reported that Nox4 is the major source of ROS in the kidneys during the early stages of diabetes mellitus and Nox4-derived ROS are considered to mediate renal hypertrophy, increase fibronectin expression and myofibroblast activation induced by TGFβ1." (PMID 23991195, 2013). "Since Nox4 is the major source of ROS production in the kidneys during the early stages of diabetes, the level of nitrotyrosine, as a marker of ROS production and the levels of 8-OHdG, as a marker for ROS induced DNA damage, were determined in diabetic mice in the presence and absence of plumbagin." (PMID 23991195, 2013). "In this study we hypothesise that targeting Nox4 in diabetes mellitus will decrease ROS generation and mitigate the development of renal pathology." (PMID 23991195, 2013). "However, our in vitro results, coupled with our in vitro data, suggest that elevated levels of TGFβ, as observed in diabetes, increases Nox4 expression that drives the development of tubulointerstitial pathology." (PMID 23991195, 2013). "Since Nox4 is the major source of ROS in the kidneys during the early stages of diabetes, interventions to reduce ROS production by targeting Nox4 or increasing SOD1 may be an attractive therapeutic strategy." (PMID 23991195, 2013). "Conversely, the induction of three genes, Nox1, Nox4, and Txnip, by diabetes plausibly contributes to pathology by producing oxidative stress, and the complete reversal of the elevation of these genes by the ketogenic diet plausibly contributes to the reversal of neuropathy." (PMID 21533091, 2011). "However, whether NOX4 or other NADPH oxidases cause ferroptosis in β-cells and thus induce or exacerbate diabetes needs further validation." (PMID 38693581, 2024). "Additionally, STZ-diabetic NOX4-/ApoE-deficient mice have no change in atherosclerosis development after 10 weeks; however, after 20 weeks of diabetes, there was a significant elevation in atherosclerotic development through increased SMC proliferation." (PMID 32923955, 2019). "NOX4 activation during the onset of insulin resistance is likely increased to enhance vascular hyperpolarizing effects and insulin signaling effects; whereas advanced diabetes progression hampers the beneficial effects of NOX4, with oxidative stress instead being induced." (PMID 31382355, 2019). "After 4-weeks of diabetes, diabetic Hhip+/+ animals had evidence of renal hypertrophy, increased GFR and urinary ACR, and developed DN features including glomerulosclerosis, glomerular fibrosis and podocyte loss (co-IF staining with p57 and Hhip), as well as elevated oxidative stress (Nox4-IHC)." (PMID 29654303, 2018). "The increase in NOX-4 expression and ROS levels observed in smooth muscle of ob/ob mice or in smooth muscle treated with HG could be due to a decrease in miR-25 expression in diabetes." (PMID 28678840, 2017). "A renoprotective effect has also been reported where the activation of adenosine monophosphate-activated protein kinase (AMPK) by cocoa enriched polyphenols followed by reduction in NOX4/TGFβ-1 signaling may have a therapeutic potential in diabetic nephropathy in experimental diabetes mellitus." (PMID 27599802, 2016). "Moreover, the finding of similar levels of NOX4 expression and activity in non-diabetic mice displaying different genotypes suggests that NOX4 overexpression during diabetes is selectively linked to the lack of EDA domain." (PMID 27897258, 2016). "Furthermore, Nox4 has recently been reported to localize within mitochondria but if Nox4 is a major source of mitochondrial ROS generation in diabetes remains unknown." (PMID 25367693, 2014).